AR (androgen receptor)
Diseases named in the same sentence as AR in open-access papers (continued):
Sharing a sentence is not in itself a finding about the gene and the disease.
ovarian carcinoma (continued). "Notably, a number of studies showed that AR is overexpressed in ovarian cancer." (PMID 26318424, 2015). "However, it is uncertain whether AR activity is an important target of taxol in treatment of ovarian cancer." (PMID 26318424, 2015). "Furthermore, silencing the driver genes sensitized other ovarian carcinoma cell lines to taxol; for instance, knockdown of the AR sensitized MDAH-2774 and TOV21G cell lines to taxol at levels similar to those observed for SKOV3/Tx600 cells (SF50 = 2.2 and 2.9, respectively; data not shown)." (PMID 26318424, 2015). "As demonstrated in in vitro ovarian cancer cell models, TLR4/IL‐6 provokes AR expression via the PI3K/AKT signaling pathway, among which phosphorylated AKT is essential for the expression of AR." (PMID 40968783, 2026). "In epithelial ovarian cancer (EOC), AR is expressed more often than ER and has been reported to be detectable in up to 90% of cases." (PMID 39598525, 2024). "Since miR-449a and miR-449b-5p suppress CSF1R and AR expression in ovarian cancer cells (SKOV3 and Hey) and CSF1R and AR are associated with the risk of ovarian cancer development, we next tested whether these miRNAs could exert any noticeable effects on the behavior of ovarian cancer cells." (PMID 39622842, 2024). "For example, Src inhibitor can block IL-8-induced AR transcription, indicating that IL-8 induces AR transcription through Src in SKOV-3 cell which is a cell model of epithelial ovarian cancer (EOC)." (PMID 35886904, 2022). "These co-regulators including coactivators and corepressors modulate AR activity and activate ARE-mediated transcription in ovarian cancer cells, although most of them also interact with other receptors." (PMID 35886904, 2022). "PCR analyses also showed the presence of the AR transcript in 2 of 4 primary cultures from ovarian cancer and 1 (i.e., SKOV3) of 3 established ovarian cancer cell lines." (PMID 30791431, 2019). "In this study, AR expression and degrees of increased signaling activity in response to an androgen agonist, DHT, varied among the six ovarian cancer cell lines." (PMID 34926721, 2019). "We sought to evaluate androgen receptor (AR) and PI3K pathway activity in ovarian cancer cell lines and tissue and determine if either pathway was correlated with growth of ovarian cancers." (PMID 34926721, 2019). "In this study, we quantified the expression and activity of AR and PI3K/AKT pathways in ovarian cancer cell lines and tumor tissue samples and examined the sensitivity of the cell lines to enzalutamide and metformin." (PMID 34926721, 2019). "AR and Nanog expression signals in the GFP (+) ovarian cancer cells were detected via confocal laser scanning microscopy." (PMID 29716628, 2018). "Additionally, androgen-induced epithelial ovarian cancer proliferation may be partially due to the enhanced IL-6 and IL-8 expression, which could also promote epithelial ovarian cancer growth via activation of the AR gene promoter." (PMID 27741511, 2017). "We have recently established AR over-expressing OVCAR-3 and SKOV-3 ovarian cancer cell lines and evaluated their effect on proliferation and migration in vitro." (PMID 27741511, 2017). "The remaining 10 genes havenot been investigated in ovarian cancer and include SFPQ which hasbeen suggested to function as an androgen receptor co-regulator." (PMID 21423607, 2011). "Androgen promotes tumorigenesis in some cancers; however, androgen receptor (AR) is not commonly examined in ovarian cancers (OCs)." (PMID 40392873, 2025). "Knockdown of Gli3 suppresses the proliferation and migration of androgen receptor-positive breast and ovarian cancer cells, which does not occur for androgen receptor-negative cells." (PMID 41018112, 2025).
ovarian carcinoma (continued). "Our present study bridges this knowledge gap by showing how these miRNAs modulate the expression of CSF1R and AR in ovarian cells, implicating their significant roles in regulating CSF1/CSF1R and AR signaling pathways during the development of epithelial ovarian cancer in HR women." (PMID 39622842, 2024). "An inexpensive evaluation method of AR, ESR, and PR expression and co-expression alongside the proliferation index could be applied to patients with ovarian carcinoma and correlated with survival rates." (PMID 32785177, 2020). "A significant positive correlation between Rab25 and AR expression was also found in ovarian cancer specimens, although there is no direct evidence indicating that androgens regulate the expression/activity of Rab25." (PMID 30791431, 2019). "We hypothesized that this reciprocal relationship between the AR and PI3K/AKT pathways would exist in ovarian cancer and if present, may respond to treatment with dual suppression." (PMID 34926721, 2019). "2A), suggesting again that these cells are not dependent on AR for growth and that a reciprocal interaction between PI3K and AR signaling does not occur in ovarian cancer cells." (PMID 34926721, 2019). "AR expression and activity did not predict the dependence of ovarian cancer cell lines on androgens for growth, and AR expression and activity did not correlate with PFS." (PMID 34926721, 2019). "In summary, in our evaluation of 6 ovarian cancer cell lines and 51 ovarian cancer patient tissue samples, AR expression and AR activity did not consistently correlate with each other, growth of cancer cells, or PFS." (PMID 34926721, 2019). "Assessment of additional markers of AR and PI3K signaling, and use of PI3K inhibitors that are more selective than metformin, would be useful to clarify the relationship between these pathways in ovarian cancer." (PMID 34926721, 2019). "Since treatment with DHT or ASC-J9 did not induce ovarian cancer cell death, our results indicate that androgen induced Nanog gene promoter activity in ovarian cancer cells through the AR signaling axis." (PMID 29716628, 2018). "A handful of clinical trials testing AR-signaling inhibitors in women with ovarian cancer have been completed, with no clear signs of activity." (PMID 28085048, 2017). "Using a cut-off of 10%, only AR showed a significant difference of expression (p=0.013) between the two studied series: the risk to develop a brain metastasis appeared 9.5 times greater in patients with AR-negative primary ovarian cancer." (PMID 28467804, 2017). "Our results indicate that a normal level of FKBP5 is able to stabilize AR or lead to its accumulation in ovarian cancer as well as in non-cancer HEK293T cells." (PMID 25460502, 2014). "This is consistent with expression of AR, PR, ERα, and ERβ in human ovarian cancer cell lines and normal OSE." (PMID 23460878, 2013). "These pathways may be more responsive to flutamide treatment in ovarian cancer cells than in primary cells, through mechanisms dependent on or independent of flutamide’s antiandrogen effect on the AR pathway." (PMID 39622842, 2024). "Introducing mimics of these miRNAs reduced the mRNA and protein levels of AR and colony-stimulating factor 1 receptor (CSF1R, also known as c-fms), both of which are known contributors to ovarian cancer progression, with emerging evidence also supporting their roles in ovarian cancer initiation." (PMID 39622842, 2024). "ER and PR are generally included in the pathologic examination of ovarian cancer, but not AR." (PMID 33891016, 2021). "However, IU1 did not significantly affect cell growth in the present study, which suggested that USP14 is not critical in ovarian cancer and implied the lack of USP14-mediated androgen receptor signaling in ovarian cancer progression." (PMID 31666925, 2019). "However, addition of enzalutamide, the AR inhibitor, to the ovarian cancer cells did not increase levels of phospho-mTOR (Figure." (PMID 34926721, 2019).
ovarian carcinoma (continued). "However, the therapeutic efficacy of the androgen/AR blocking reagents used in those tests were not significant, or were inconclusive in regards to ovarian cancer therapy." (PMID 30986993, 2019). "However, the impact of AR has not been widely pursued in ovarian cancer, and to date, the precise roles of AR and CSCs in ovarian cancer are not fully understood." (PMID 29716628, 2018). "However, as it stand, the prognostic impact of AR expression in epithelial ovarian cancers is not clear." (PMID 28085048, 2017). "We also found that AR binds the Akt-dependent FKBP5 immunophillin, enhancing its transactivation activity, an observation which suggests that this protein may represent a key marker of txr in ovarian cancer cells." (PMID 26318424, 2015). "Interestingly, flutamide did not prevent DHT-induced p27 degradation, and other androgens, including testosterone and DHEA, failed to affect p27 expression/degradation, suggesting that DHT modulates the cell cycle progression of ovarian cancer not via the traditional AR pathway." (PMID 30791431, 2019). "Thus, AR is detected more so in serous than non-serous ovarian tumors but whether AR expression level is important for ovarian cancer progression remains to be determined." (PMID 27741511, 2017). "Spatial proteomics showed a negative correlation between AR and CD45 protein in sarcoma and ovarian cancers." (PMID 41486951, 2026). "Notably, AR expression showed a moderate negative correlation with CD45, a general marker of leukocytes, in both patients with ovarian cancer and SARC." (PMID 41486951, 2026). "In addition, binding of DHT to the AR with high affinity and low capacity was documented in not only OVCA3 but also other human ovarian cancer cell lines, including SKOV3 and HEY." (PMID 30791431, 2019). "While our study did not support robust reciprocal feedback between AR and PI3K/AKT pathway activity in ovarian cancer, the small sample may prevent this finding from being extrapolated and further studies are warranted in different ovarian cancer histologies." (PMID 34926721, 2019). "Evaluation of AR protein expression in 154 EOC cases from two large, prospective population-based studies demonstrated frequent expression of AR in fallopian tube epithelium irrespective of the presence of ovarian cancer and decreased AR expression in primary ovarian tumors and metastatic deposits." (PMID 20565760, 2010).
benign prostatic hyperplasia (97 papers, 2005 to 2026). A non-cancerous nodular enlargement of the prostate gland. "Binding of DHT to the androgen receptor (AR) has been reported to cause prostatic enlargement through diverse pathophysiological mechanisms." (PMID 41473249, 2025). "It was reported that BRD2/4 and ATAD2, both co-activators of AR, mediate increased chromatin accessibility and AR association with chromatin in CRPC compared with benign prostate hyperplasia, potentially contributing to enzalutamide resistance." (PMID 40833121, 2025). "The finding that AR suppresses proliferation in the adrenal cortex might seem surprising, given the well-characterized association of AR with prostate growth, benign prostate hyperplasia and prostate tumorigenesis." (PMID 37102205, 2023). "On the other hand, overproduction of DHT by SRD5α2 is associated with benign prostatic hyperplasia (BPH), androgenic alopecia and prostate cancer due to excessive androgen receptor signaling." (PMID 32702725, 2020). "NFI family proteins are suggested to repress the expression of AR target genes, and knockdown of NFIB is shown to cause benign prostate hyperplasia, suggesting a role in the initiation of PCa." (PMID 40833121, 2025). "They managed to suppress the expression of AR when the prostate hyperplasia of Sprague Dawley was treated with Cinnamomum Cassia and Rosa Laevigata mixture." (PMID 40115867, 2025). "Since 5AR is important for prostatic hyperplasia development and is able to downregulate the level of AR, these results concluded that the cinnamon cortex can be a potential pharmaceutical therapy for BPH treatment." (PMID 40115867, 2025). "The 70% ethanol extract of A. distichum leaves (ADE) demonstrated stronger inhibition of androgen receptor signaling than did the extracts from distilled water and 95% hexane, indicating its potential to prevent prostatic hyperplasia." (PMID 40761499, 2025). "Recent studies show that macrophages have a role in immune inflammation and proliferation in benign prostatic hyperplasia through the androgen receptor and CD40/CD40L signaling pathway." (PMID 39703506, 2024). "Genomic studies have suggested that FOXA1 regulates the expression of AR and that deletion of FOXA1 in the luminal epithelium of adult mice causes prostatic hyperplasia." (PMID 38778357, 2024). "Many studies have shown that androgen/androgen receptor (AR) signaling plays a crucial role in prostatic hyperplasia." (PMID 38538986, 2024). "Beyond cancer, the beneficial effects of MitoQ on various diseases have been previously documented, including the inhibition of prostatic hyperplasia via androgen receptor and NOD-like receptor family pyrin domain-containing 3 inhibition." (PMID 38732133, 2024). "In the prostate, 5 α-reductase converts testosterone into dihydrotestosterone, which in turn combines with the androgen receptor to promote prostatic hyperplasia." (PMID 36920576, 2023). "Steroid signalling through the androgen receptor is considered to be the key regulator of prostatic hyperplasia." (PMID 36920576, 2023). "AR derived protein expression has been investigated by immunohistochemistry in benign prostatic hyperplasia and PCa tissue." (PMID 33599076, 2021). "The relative expression of N-cadherin, NDRG1, and AR was evaluated in prostate hyperplasia (BPH-1), androgen-dependent PCa (ADPC) (LNCaP), and CRPC (PC3) cell lines." (PMID 34512147, 2021). "It is known that the blockade of AR can decrease benign prostate hyperplasia (BPH) symptoms and further relieve the lower urinary tract symptoms." (PMID 33917905, 2021). "On the other hand, overproduction of DHT by SRD5A2 is associated with benign prostatic hyperplasia (BPH), androgenic alopecia, and prostate cancer due to excessive androgen receptor signaling." (PMID 33110062, 2020). "Current research has been focused on a relationship between the disease severity and AR regulatory pathway mediated by SRD5A1 overexpression in benign prostatic hyperplasia and PC." (PMID 32983992, 2020).
benign prostatic hyperplasia (continued). "The factors related to prostatic hyperplasia were examined by western blot assays using antibodies against 5AR and AR." (PMID 31467577, 2019). "The activation of androgen receptor (AR) signaling plays an essential role in both prostate stromal cells and epithelial cells during the development of benign prostatic hyperplasia (BPH)." (PMID 29568063, 2018). "The current study evaluated the anti-oxidative and anti-inflammatory activities and 5α-reductase inhibition of isolated compounds of AR leaves to find a potential therapeutic agent for benign prostatic hypertrophy (BPH)." (PMID 27399661, 2016). "Because 5AR is an important trigger creating prostatic hyperplasia and AR is the main receptor related to 5AR and DHT, these results suggest a potential pharmaceutical therapy of CC on BPH treatment." (PMID 27549514, 2016). "According to data from the Health Professionals Follow-Up Study, men with AR gene CAG repeat lengths of 19 or less had an OR of benign prostatic hyperplasia of 1.92 relative to men with repeat lengths of 25 or more." (PMID 26421011, 2015). "AR-activation in benign prostatic hyperplasia was only recently demonstrated produce anti-inflammatory effects." (PMID 23805952, 2013). "Androgen receptor activation exerts the anti-inflammatory effect on human benign prostatic hyperplasia cells." (PMID 24194757, 2013). "Therefore, it is highly suspected that AR interacts directly or indirectly with mitochondria to change mitochondrial function and induce prostatic hyperplasia in OEx mice." (PMID 38538986, 2024). "Additionally, NFIB has been found to interact with FOXA1 as a cofactor in regulating AR target gene expression, and loss of NFIB induces prostatic hyperplasia in a mouse model." (PMID 38778357, 2024). "By increasing oestrogen to androgen ratios, upregulated AR expression may increase the sensitivity of the prostate to androgens, resulting in prostate hyperplasia." (PMID 36920576, 2023). "A high level of AR is specific for both PCa and benign prostatic hyperplasia (BH)." (PMID 32102520, 2020). "When the ratio of estrogen to androgen is increased, the upregulated AR expression might increase the sensitivity of the prostate to androgens, thereby promoting prostate hyperplasia." (PMID 32753632, 2020). "The role of molecular changes in the androgen receptor (AR) as AR variants (AR-Vs) is not clear in the pathophysiology of benign prostatic hyperplasia (BPH) and hormone-naïve PCa." (PMID 30028845, 2018). "In this study, we showed that the botanical formulation HX109 could ameliorate TP-induced prostate hyperplasia by controlling androgen receptor signaling." (PMID 30544543, 2018). "The prostatic hyperplasia was examined by IHC staining using antibodies against 5AR, AR, and SRC-1." (PMID 30061836, 2018). "Small sampling size and non-matched African American and Caucasian American tissue specimens used in this pilot study may account for the similarity of AR expression in benign prostate hyperplasia." (PMID 15888205, 2005). "DHT plays a central role in the pathogenesis of benign prostatic hyperplasia (BPH) by continuously activating the androgen receptor signaling pathway and promoting the proliferation of prostate epithelial cells." (PMID 40626307, 2025). "We conducted this study to investigate the effects of CBP on AR expression and proliferation in benign prostatic hyperplasia (BPH) prostate epithelial cells." (PMID 38002029, 2023). "In the human prostate gland, several progestins, including chlormadinone, and osaterone, were found to reduce the volume of benign prostatic hyperplasia (BPH) mass due to shrinkage of glandular and stromal compartments by antagonizing the AR signaling pathway." (PMID 34572596, 2021).